MIF (macrophage migration inhibitory factor)
Diseases named in the same sentence as MIF in open-access papers (continued):
Sharing a sentence is not in itself a finding about the gene and the disease.
breast cancer (continued). "Second, through comprehensive multi‐omics analysis and in vitro experiments, tumor cell‐derived GA‐dependent migration inhibitory factor (MIF) was identified to play a crucial role in mediating the formation of an immunosuppressive network in breast cancer (BRCA)." (PMID 39908165, 2025). "To confirm the hypothesis, we performed MIF knockdown in MDA-MB-231 human breast cancer cells using shRNA technology (sh-MIF), with scrambled shRNA serving as a negative control (NC)." (PMID 40695812, 2025). "Studies have demonstrated that macrophage migration inhibitory factor (MIF), secreted by breast cancer stem cells (BCSCs), activates the WNT/β-catenin signaling pathway to upregulate c-MYC-mediated expression of aldolase C, thereby promoting glycolytic metabolism in tumor cells." (PMID 40342932, 2025). "Moreover, MIF expression was elevated in advanced stages and more aggressive molecular subtypes of breast cancer, showing a strong correlation with IL-17 levels." (PMID 41159021, 2025). "Considering these findings, it is quite likely that the inhibition of MIF expression by the PARPis may contribute to the reversion of the TAM phenotype in breast cancer." (PMID 38612413, 2024). "Similarly, MIF was highly present in 30% of breast cancer samples, while this was true for only 5% of the normal breast tissue samples." (PMID 36672343, 2023). "Indeed, a MIF knockout breast cancer cell line led to smaller tumors upon injection in mice compared with the control cell line." (PMID 36672343, 2023). "Macrophage migration inhibitory factor (MIF) pathway was active between EDCs and immune cells in both lymph nodes and primary tumors, indicating it is essential in both sites and likely to contribute to breast cancer dissemination." (PMID 36594618, 2023). "These functions of MIF were confirmed in a MIF knockout breast cancer cell line." (PMID 36672343, 2023). "In a model of breast cancer, elevated MIF expression supported tumor growth while a loss of MIF promoted the anti-tumor immune infiltration of CD4+/CD8+ T cells producing IFNγ, which supported the MIF immunosuppressive function." (PMID 36496973, 2022). "We previously identified MIF as an Hsp90-stabilized protein in breast cancer cells." (PMID 33542244, 2021). "MIF can effectively inhibit breast cancer cell apoptosis by activating PI3K/AKT pathway." (PMID 34485124, 2021). "This suggests a probable role for the miR-451a/MIF pathway in the biology of breast cancer cells." (PMID 33925125, 2021). "A gene expression analysis of 17 healthy women showed that VAT has a distinct metabolic function that can produce pro-inflammatory cytokines, including CC chemokine receptor 2 and macrophage migration inhibitory factor, and this potentially leads to breast cancer progression." (PMID 33557032, 2021). "Overexpression of MIF in breast cancer is closely related to tumor growth and metastasis." (PMID 34485124, 2021). "In another study, BG34-10 glucan was identified to mediate specific and active internalization of NPs by primary macrophages, and was able to effectively deliver MIF siRNA to TAMs within 4T1 mammary tumors and reduce their MIF expression following systemic administration." (PMID 34716900, 2021). "Prognostic significance of MIF expression in breast cancer was assessed by a comprehensive analysis of MIF expression in human TNBC samples using TMAs that contained 100 patient samples with 61 TNBC tumor samples and 39 adjacent normal samples by immunohistochemistry." (PMID 32943608, 2020). "Furthermore, using TCGA dataset, we found that MIF expression was elevated in TNBC patient samples compared to other hormonal breast cancer subtypes." (PMID 32943608, 2020).
breast cancer (continued). "Furthermore, MIF overexpression correlated with worse survival in TNBC compared to other breast cancer subtypes." (PMID 32943608, 2020). "MIF has been shown to promote breast cancer growth and metastasis." (PMID 32943608, 2020). "In addition, elevated MIF expression was observed in invasive ductal breast carcinoma patients compared to healthy individuals in Curtis breast cancer dataset." (PMID 32943608, 2020). "These phenomena may be illustrated by the observations that MIF secretion increased after ROS production, as was demonstrated in clear cell renal cell carcinoma, breast cancer, and lung cancer." (PMID 30634708, 2019). "Several studies have elucidated the multiple roles of MIF in the breast cancer microenvironment, including increasing the recruitment of immunosuppressive cells (Simpson, Templeton & Cross, 2012), inducing angiogenesis and breast cancer cell trans-endothelial migration." (PMID 31293831, 2019). "Over-expression of miR-451a could inhibit cell proliferation and enhance tamoxifen sensitivity in breast cancer by regulating 14-3-3ζ, estrogen receptor α, and macrophage migration inhibitory factor." (PMID 32038996, 2019). "Interestingly, MIF has recently been shown to be instrumental in promoting tumor growth and metastasis in breast cancer." (PMID 31036057, 2019). "CXCL12 together with macrophage migration inhibitory factor (MIF) were chosen also to explain stimulation of adhesion and trans-endothelial migration of human breast cancer cells by irradiation of lung cells on the basis of a high fold change found in a 52 cytokine secretome assay." (PMID 30134800, 2018). "In breast cancer, the cytokines concerned with the differentiation of MDSCs from bone marrow progenitors include G-CSF, M-CSF, GM-CSF, IL-6, IL-1β, macrophage migration inhibitory factor (MIF), TGF-β1." (PMID 27542274, 2016). "Significantly increased levels of MIF were detected in plasma from patients with ovarian cancer (median 9.6 ng/ml), prostate cancer (median 8.9 ng/ml), breast cancer (median 8.4 ng/ml), head and neck cancer (median 8.3 ng/ml) and renal cell carcinoma (median 10.1 ng/ml)." (PMID 27636991, 2016). "In addition, the study also found that in breast cancer cells, MIF regulates secretion of VEGF-C by influencing stepwise phosphorylation of p38-MAPK and ERK1/2 two classic MAPK signaling pathways." (PMID 26911617, 2016). "Blocking of MIF activity either by antibodies or stable RNA interference reduced tumor growth in animal models of colorectal cancer, prostate cancer, ovarian cancer, neuroblastoma, pancreatic cancer, breast cancer, melanoma and lung cancer." (PMID 27636991, 2016). "Among these genes, extracellular MIF has been shown to act as a pro-oncogene in breast cancer." (PMID 25942583, 2015). "In conclusion, our data support the concept of a functional role of MIF in human breast cancer." (PMID 24939415, 2014). "As previously reported, MIF expression may be induced by epidermal growth factor (EGF) in breast cancer cells and also appears to be involved in the proliferative pathway activated by EGF." (PMID 25289107, 2014). "The serum MIF level was also determined in breast cancer patients." (PMID 24939415, 2014). "In parallel, the serum level of MIF was determined in breast cancer patients." (PMID 24939415, 2014). "Finally, macrophage inhibitory factor (MIF) was found to be downregulated in breast cancer skeletal metastases compared with the primary mammary tumors." (PMID 23174366, 2012). "It has been shown that MIF promotes breast cancer cell proliferation, angiogenesis, and survival." (PMID 23174366, 2012). "However, although MIF was frequently overexpressed in primary mammary tumor tissues, its presence was inversely correlated with the nodal spread of breast cancer." (PMID 23174366, 2012). "In addition, nm23-H1 is a negative regulator of the Macrophage Induced Factor (MIF), a cytokine with anti-apoptotic properties, in particular in breast cancer cells." (PMID 21490937, 2011).
breast cancer (continued). "It was reported that hypoxia (1% O2) stimulation could induce MIF expression in breast cancer cell line." (PMID 20727156, 2010). "Thus, while there is consensus from these reports that MIF is overexpressed in human breast cancer, its functional correlation with breast tumourigenesis has remained unclear." (PMID 19602265, 2009). "The best features to detect breast cancer were MIF, MMP-9, and MPO." (PMID 19476629, 2009). "Indeed targeting MIF by neutralizing antibody has recently been shown to enhance chemotherapy efficacy in breast cancer cells." (PMID 20038293, 2009). "Thus, invasive breast cancer cells exhibiting low MIF expression and secretion levels at baseline are capable of dramatically upregulating MIF upon short term triggering with exogenous MIF, possibly derived from tumour/stroma interactions." (PMID 19602265, 2009). "Only a few studies have addressed the role of MIF in breast cancer." (PMID 19602265, 2009). "MIF was upregulated in breast cancer versus normal tissue (median IRS = 8 versus 6)." (PMID 19602265, 2009). "This suggested that invasive breast cancer cells are target cells of MIF in breast cancer." (PMID 19602265, 2009). "Thus, MIF de novo synthesis and intracellular protein storage differ between normal epithelial and breast cancer cells and highly invasive cells produce low concentrations of this cytokine." (PMID 19602265, 2009). "Patients with strong cytosolic MIF expression in the breast cancer tissue (IRS = 6–12) showed a highly significant increase in overall survival (OS) compared to the MIF low expresser group with an IRS = 0–4 (5-year OS = 67% versus 50%, respectively; p = 0.0019)." (PMID 19602265, 2009). "In conjunction, these prior and in part conflicting studies indicate that despite its established overexpression in breast cancer, the contribution of MIF to breast cancerogenesis is likely to be complex and may vary between disease stages." (PMID 19602265, 2009). "This hypothesis is underscored by the finding that breast cancer patients with abundant MIF expression have a favourable prognosis both according to tumour-specific OS and RFS." (PMID 19602265, 2009). "The obtained correlation between MIF expression in breast tumour tissue and tumour size and hormone receptor levels tempted us to postulate that MIF overexpression might be correlated with increased tumour-specific survival in breast cancer patients." (PMID 19602265, 2009). "Thus, in cycling breast cancer cells, MIF production and secretion rates exceeded re-endocytosis and degradation." (PMID 19602265, 2009). "MIF levels in breast cancer cell lines were determined by ELISA and Western blot." (PMID 19602265, 2009). "We conclude that intracellular expression of MIF in breast cancer cells is beneficial, whereas extracellular MIF may play a pro-oncogenic role in promoting breast cancer cell-stroma interactions." (PMID 19602265, 2009). "Intracellular MIF localised to breast cancer cells may be indicative of a favourable prognosis, whereas extracellular breast tumour tissue-derived MIF could be proinflammatory and will likely constitute an unfavourable prognosis marker." (PMID 19602265, 2009). "To begin to study potential amplifying effects of exogenous MIF, i.e. MIF released in the tumour microenvironment by TAMs or breast cancer cells themselves, we examined the secretion of MIF in unstimulated breast cancer cells and in those exposed to exogenous recombinant MIF (rMIF)." (PMID 19602265, 2009). "Moreover, we undertook a comprehensive study correlating MIF expression levels in 175 breast cancer specimens with clinicopathological parameters and patient outcome data including overall (OS) and recurrence-free survival (RFS)." (PMID 19602265, 2009). "The precise role of macrophage MIF in breast cancer development and treatment response remains unknown, but MIF has been implicated in tumor cell survival pathways." (PMID 18474099, 2008).
breast cancer (continued). "Given the axis’s potential role in promoting EMT, cellular migration, and survival signaling, targeting the WISP1/Src/MIF pathway presents a promising therapeutic approach to combat aggressive ER-Positive breast cancer and may help overcome treatment resistance." (PMID 41597235, 2026). "Furthermore, the WISP1/Src/MIF axis may serve as a clinically relevant biomarker to stratify patients and guide targeted therapeutic strategies in ER+ breast cancer." (PMID 41597235, 2026). "However, this basal MIF secretion was not linked to the invasive phenotype in the studied mouse breast cancer cell lines." (PMID 41159021, 2025). "The role of MIF/CD74 in lung metastasis of breast cancer and whether the combination of MIF inhibitors and AEP inhibitors is safer and more effective than the chemotherapy drug combination regimen used in previous studies (AEP inhibitors + epirubicin) are still unknown." (PMID 40411322, 2025). "Therefore, laboratory validation both in vivo and in vitro is envisioned to illuminate the detailed molecular mechanism, and prospective clinical validation with studies involving larger cohorts of breast cancer patients is required to confirm the prognostic value of serum MIF levels." (PMID 38916819, 2024). "However, there have been many contradictory results reported regarding whether MIF has growth inhibition or stimulation for hormone-responsive breast cancer cells, as an anti-progestin." (PMID 36246881, 2022). "In the breast cancer cohort, studying each factor alone, high levels of either Serpin E1 and IL-8 were associated with poor survival (p < 0.0001 and p = 0.0016, respectively), whereas high expression levels of MIF and PDGF-AA did not predict poor survival." (PMID 33158447, 2020). "Therefore, targeting MIF could be a promising strategy to target aggressive breast cancers, including TNBC." (PMID 32943608, 2020). "Interestingly, CD74 or MIF blockade reduced the aggressiveness of invasive breast cancer cells." (PMID 32943608, 2020). "Apart from that, downregulation of miR-451a is also able to upregulate MIF expression and can increase breast cancer cell growth, invasion, and tamoxifen sensitivity, which indicated that the miR-451a/MIF pathway may also be a potential therapeutic target for breast cancer as well as IBC." (PMID 30733644, 2019). "Thus, there appears to be a dichotomy of MIF functions in breast cancer progression." (PMID 19602265, 2009). "Thus, CD74 appears to be primarily expressed in invasive breast cancer cells, indicating that such tumour cells may be prone to stimulation with MIF." (PMID 19602265, 2009). "In turn, as manifest from the study of Hagemann, breast cancer cell-derived MIF might then modulate (pro-invasive) TAM activities as well as induce a broad range of inflammatory processes, including the elevated expression of secondary mediators that may further promote tumourigenesis." (PMID 19602265, 2009). "Thus, MIF secretion from breast cancer cells could be strongly influenced by auto- or paracrine MIF effects in the tumour-stroma microenvironment." (PMID 19602265, 2009). "The present study establishes WISP1 as a nexus linking intracellular signaling to microenvironmental remodeling and identifies Lyn, MIF/CD74, and HA metabolism as promising therapeutic targets in breast cancer." (PMID 41597235, 2026). "Therefore, combination therapy utilising AEP‐targeted inhibitors and CD74/MIF pathway inhibitors may provide comprehensive inhibition of distant organ metastasis in breast cancer, potentially emerging as a promising clinical strategy for future therapeutic development." (PMID 40411322, 2025). "Elevated sera and tumor MIF and DDT levels have been observed in breast cancer, validated by cell lines, patient samples and murine models, and are correlated with worse survival." (PMID 38732068, 2024).
breast cancer (continued). "Another study identified that breast cancer patients showed elevated plasma levels of cytokines CCL27 and macrophage migration inhibitory factor (MIF) following two cycles of Dox." (PMID 38987722, 2024). "Elevated MIF also has been found in triple-negative breast cancer (TNBC), a highly aggressive breast cancer subtype." (PMID 38732068, 2024). "MIF and PRG can act as negative regulators of proliferation in breast cancer cells and as negative regulators of apoptosis to protect neuronal cells." (PMID 36984647, 2023). "One of these cytokines is macrophage migration inhibitory factor (MIF), which is a direct target gene of HIF-1α and a hypoxia-induced gene in colon and breast cancer cells." (PMID 36496973, 2022). "A study in breast cancer patients receiving Dox found that the plasma levels of cytokines CCL27 and macrophage migration inhibitory factor (MIF) were elevated after two cycles of Dox." (PMID 36498974, 2022). "According to previous reports, the inhibition of autophagy in TNBC cell lines induces the secretion of the macrophage migration inhibitory factor (MIF), thereby promoting breast cancer invasion and immunomodulation." (PMID 35321516, 2022). "In in vitro experiments, overexpression of miR-451a reduced the expression of target gene macrophage migration inhibitory factor (MIF) and suppressed cell proliferation, colony formation, and invasion of breast cancer cells." (PMID 33925125, 2021). "We found that the inhibition of autophagy in TNBC cell lines induced the secretion of the macrophage migration inhibitory factor (MIF), a pro-tumorigenic cytokine involved in breast cancer invasion and immunomodulation." (PMID 31963754, 2020). "Relationship between MIF, VEGFA expression level, and clinico-pathologic parameters of breast cancer by tissue microarray." (PMID 31293831, 2019). "Recent studies provided evidence that MIF is necessary for the immunosuppressive function of TAM and MDSCs in breast cancer and melanoma." (PMID 29285252, 2017). "G-CSF, M-CSF, IL-6, MIF and TGF-β1 were verified to promote the differentiation of myeloid cells into MDSCs in 4T1 mammary tumor BALB/c mice." (PMID 27542274, 2016). "Following profiling of MIF expression, we proceeded to map CD74 in breast cancer and in tumor-free tissue." (PMID 24939415, 2014). "Thus, rMIF promotes the migration and invasion of breast cancer cells through basement membrane-like layers in a chemokine-like manner, confirming the notion that MIF produced in the microenvironment surrounding breast tumour cells may act in a pro-invasive manner." (PMID 19602265, 2009). "Furthermore, the tremendous increase in the rate of MIF secretion as observed in breast cancer cells following stimulation with rMIF suggests that TAM-derived MIF could trigger MIF secretion from breast cancer cells, thus igniting a local MIF amplification loop." (PMID 19602265, 2009). "While we confirmed that MIF was markedly overexpressed in non-invasive MDA-MB-468 and ZR-75-1 breast cancer cells, compared to benign MCF-12A breast cells, the highly invasive MDA-MB-231 cancer cells surprisingly showed low MIF expression levels." (PMID 19602265, 2009). "It is of note that the breast cancer cell type exhibiting the highest overall (surface + endolysosomal) CD74 expression levels, showed the greatest response to MIF." (PMID 19602265, 2009). "In this study, we demonstrate that intracellular overexpression or extracellular administration of MIF increased HIF-1α protein expression and HIF-1-dependent gene expressions in MCF-7 breast cancer cells." (PMID 18493321, 2008). "Importantly, the present study highlights the novel contribution of identifying the WISP1/Src/MIF signaling axis as a key regulator of HA metabolism and EMT in ER+ breast cancer, providing new mechanistic insights into tumor plasticity and aggressiveness." (PMID 41597235, 2026).